CCND1 (cyclin D1)
Diseases named in the same sentence as CCND1 in open-access papers (continued):
Sharing a sentence is not in itself a finding about the gene and the disease.
cancer (continued). "Therefore, studies are still required to elucidate effective knock-down methods directed towards cyclin D1 itself for use as cancer therapy." (PMID 25437003, 2014). "One endogenous targets Cyclin D1 of the c-Myc in cancer cells were tested." (PMID 24991193, 2014). "Deregulation of cyclin D1 has been observed to occur in a variety of cancer types including HNSCC." (PMID 25437003, 2014). "The gene for cyclin D1 is located on chromosome 11q13 and is related to various cancers." (PMID 24618206, 2014). "CCND1 is another potential molecular biomarker as a predictor of cancer prognosis." (PMID 25202398, 2014). "Thus, when miR-503 is overexpressed in cancer cells, cyclin D1 expression is downregulated and cell growth is subsequently inhibited." (PMID 24944699, 2014). "Abnormal expression of ATF3 may mediate multiple aspects of cancer biology by repressing the transcription of certain downstream molecules including Cyclin D1, Id1 and IRS2." (PMID 25149542, 2014). "Our results indicate that sgRNAs targeting human cyclin D1 may have potential therapeutic application for various types of cancers." (PMID 25437003, 2014). "Cyclin D1, a cell cycle regulator, is closely related to several human cancers." (PMID 24618206, 2014). "The disorder of CCND1 would contribute to cancer development." (PMID 25409185, 2014). "The study revealed that miR-503 could silence cyclin D1 (CCND1), a well-known proto-oncogene that is implicated in a variety of cancer types." (PMID 24944699, 2014). "Our results indicate that this could occur through a reduction in cap(eIF4E)-dependent translation of proteins essential for cancer cell proliferation (e.g. cyclin D1), survival (e.g. survivin) and genome repair (e.g. NBS1)." (PMID 24970821, 2014). "Overexpression of cyclin D1 has been reported in many cancers and it was shown that the inhibition of cyclin D1 expression could help in the cancer treatments." (PMID 24949454, 2014). "The high expression of cyclin D1 may contribute to drug resistance in cancer cells, not only by increasing cell proliferation, but also by suppressing cancer cell apoptosis." (PMID 24944679, 2014). "Downregulation of cyclin D1 in response to metformin has been shown in several cancer cell lines." (PMID 24351837, 2013). "Abnormal cell cycle regulation due to Cyclin D1 overexpression is a common occurrence in human cancers (including NPC), and both EGFR and STAT3 could target cyclin D1 promoter activity." (PMID 24499623, 2013). "Subcellular localization and stabilization of cyclin D1 play an important role in human cancers." (PMID 23786849, 2013). "Cyclin D1 is a well-known oncogene in a variety of human cancers." (PMID 23672832, 2013). "However, the mechanisms by which cyclin D1 and cyclin E1 are upregulated in cancer cells remain to be fully elucidated." (PMID 23383003, 2013). "cyclin D1 is one of the more frequently altered cell cycle regulators in cancers." (PMID 23383245, 2013). "Why will cancer cells have G1 delay with the increased cyclin D1 and cyclin E?" (PMID 23305095, 2013). "cyclin D1 over-expression is important in the development and progression of numerous cancers." (PMID 24499623, 2013). "Overexpression of Gls2 in cancer cells induced phosphorylation of the protein phosphatase cdc25c, a key regulator in the G2/M checkpoint, together with a significant reduction in p21 and cyclin D1." (PMID 24330717, 2013). "Cyclin D1, an important cell cycle regulator, is required for completion of the G1/S transition in normal mammalian cells and is one of the most commonly affected proteins in abnormal states, such as cancer." (PMID 22968658, 2013). "Sam68 also regulates AS of cyclin D1, a protooncogene frequently deregulated in cancer cells." (PMID 22666083, 2012). "Moreover, inactivation of EglN2 down-regulated Cyclin D1 and cell proliferation in several cancer cell lines." (PMID 22589739, 2012).
cancer (continued). "Recent findings from two separate studies have shown that knockdown of LZTS2 expression sensitizes cells to paclitaxel therapy in addition to antagonizing proliferation of several cancer cell lines by down-regulation of myc and cyclin D1 through engagement of the NF-κB pathway." (PMID 22606253, 2012). "Cyclin D1 (CCND1) is well known as a DNA repair gene and might sensitize human cancers to radiation by limiting DNA repair." (PMID 22846430, 2012). "We also evaluated the protein level of cyclin D1 in CGK062-treated CRT-positive cancer cells." (PMID 23071615, 2012). "Overexpression of cyclin D1 allows cells with damaged DNA or chromosome to proceed through S phase without DNA damage repair, enhancing the risk of cancer development." (PMID 22500174, 2012). "The expression of cyclin D1 in rigidity-dependent cancer cells was measured to determine whether the cells exit the cell cycle when cultured on soft gels." (PMID 22623999, 2012). "Cyclin D1 (CCND1) plays a vital role in cancer cell cycle progression." (PMID 22606291, 2012). "In addition, CGK062 repressed the expression of the genes encoding cyclin D1, c-myc, and axin-2, β-catenin target genes, and thus inhibited the growth of CRT-positive cancer cells." (PMID 23071615, 2012). "Cyclin D1, an oncogene that promotes cell cycle progression through phosphorylation of the retinoblastoma protein and prevents apoptosis by sequestering Bax in the cytoplasm has been recognized as a potential therapeutic target in cancer." (PMID 22485181, 2012). "Cyclin D1 and cyclin E are frequently up-regulated in human cancers." (PMID 23029062, 2012). "Cyclin D1 promoter activity was repressed by CGK062 in these CRT-positive cancer cells." (PMID 23071615, 2012). "Moreover, in some studies the correlation between cyclin D1 expression and proliferation was echoed in carcinomas." (PMID 22949827, 2012). "Since the expression level of Cyclin D1 is related to the potential for malignancy and the prognosis of a variety of cancers, revealing the mechanisms governing the ubiquitin-proteasome mediated degradation of Cyclin D1 is of importance in designing therapeutic interventions." (PMID 21347341, 2011). "The CCND1/CDKN2A assay predicted 5% (1/20) as RB1 (-) cancers." (PMID 21447152, 2011). "Overexpression of Bmi-1, ABCG2 and cyclin D1 and downregulation of p16 could contribute to these phenotypic changes of Panc-1 cancer stem cells." (PMID 21673909, 2011). "Curcumin has been shown to suppress the expression of cyclin D1 in many types of cancer including head and neck, colon, bladder, breast, cervical and pancreatic carcinomas, an effect attributed to curcumin's inhibition of NF-κB activation and subsequent suppression of downstream gene products." (PMID 21299897, 2011). "Thus, therole of hUCBSC in preventing cancer cell proliferation at the cellular level isevidenced by downregulation of expression of cyclin D1." (PMID 21455311, 2011). "There is evidence that defects in cyclin D1 degradation might account for the cyclin D1 protein accumulation found in cancers." (PMID 22069692, 2011). "Treatment with DMBA is known to induce p21 and cyclin-D1 in carcinoma." (PMID 21867749, 2011). "Our results showed that the loss in expression of cyclin D1/D3 inhibited proliferation and resulted in a decrease of the hyperphosphorylated/inactivated Rb in PDAC cells, consistent with the existing concept that D-cyclins drive proliferation in cancer cells." (PMID 20113529, 2010). "Cyclin D1 was identified as the Prad 1 oncogene, which is overexpressed in many types of cancer." (PMID 20424615, 2010). "Papillary thyroid carcinoma is another malignant tumour where cyclin D1 is overexpressed." (PMID 21176227, 2010). "Epidermal growth factor receptor (EGFR), p16 (CDKN2A), and cyclin D1 (CCND1), which may play an important role in the tumorigenesis and progression of this cancer, are located on chromosomes 7, 9, and 11, respectively." (PMID 20459605, 2010).
cancer (continued). "Among the candidate effectors of cyclin D1 in cancer cells is the transcription factor C/EBPβ." (PMID 20459741, 2010). "Among these types, cyclin D1 is the one most commonly expressed in several human cancers." (PMID 21176227, 2010). "However, only DR-1-stimulated CD4 or CD3 T cells possessed cytotoxicity against peptide-pulsed autologous DCs and a cancer cell line, that expresses a high level of cyclin D1." (PMID 19707583, 2009). "The association of the second CCND1 (−7006G>C) SNP with cancer or any other outcome has not been investigated previously." (PMID 19750108, 2009). "The CCHCR1 positive cancer nests in the lower dermis were cyclin-D1 positive as well." (PMID 19551138, 2009). "Alternative splicing may also contribute to cancer specific accumulation of cyclin D1 proteins that cannot undergo cytoplasmic degradation." (PMID 18764945, 2008). "Furthermore, we observed strong correlation between Ebp1 expression and the nuclear expression of AR, Cyclin D1 and ErbB3 in both normal adjacent and cancer tissues." (PMID 19025630, 2008). "Given the well-established involvement of cyclins in the regulation of cell cycle progression and the previous findings that cyclin D1 is overexpressed in many cancers and cancer cell lines, we investigated the effects of our RAMBAs on the level of cyclin D1 expression." (PMID 17387344, 2007). "The cytoplasmic sequestration of cyclin D1 may also present also a novel mechanism for regulating its activity in some cancer cell lines." (PMID 17407548, 2007). "Together these findings suggest that deregulated FBX4 activity and/or αB crystallin expression may be responsible for the increase in cyclin D1 stability observed in some cancers." (PMID 17407548, 2007). "Drug induced cyclin D1 ablation may provide a useful chemopreventive or treatment strategy for cancer." (PMID 17407548, 2007). "Our results suggest that cytoplasmic sequestration may additionally serve to regulate cyclin D1 activity in mammalian cancer cells." (PMID 16503970, 2006). "To mimic the 11q13 amplification, as seen in several human cancers, and to investigate the involvement of cortactin in mammary gland tumorigenesis and a possible cooperative action of cortactin and cyclin D1, we generated MMTV-cortactin transgenic and MMTV-cyclin D1/-cortactin bitransgenic mice." (PMID 16536875, 2006). "To test this hypothesis, we determined the subcellular localizations of FBXW8 and cyclin D1 during the cell cycle in cancer cells." (PMID 17205132, 2006). "In the late 1990's an unexpected role for cyclin D1 was uncovered, as it was established that cyclin D1 interacts with and modulates a number of transcription factors whose actions are involved in human cancers." (PMID 16863592, 2006). "We also determined the contribution of ERK/MAPK to the stability of cyclin D1 in cancer cells." (PMID 17205132, 2006). "We concluded that cyclin D1 levels are regulated by FBXW8 in the cancer cells tested here." (PMID 17205132, 2006). "This possibility suggests that high levels of MAPK activity in cancer cells may make the requirement of GSK3β redundant for cyclin D1 phosphorylation at Thr286." (PMID 17205132, 2006). "Cyclin D1 was overexpressed in 21/79 carcinomas (27%), all of which retained Rb protein." (PMID 10376969, 1999). "Therefore, the level of Cyclin D1 can serve as a biomarker for cancer diagnosis and prognosis." (PMID 40170854, 2025). "Additionally, CCND1 is also well known as an oncogene in many other cancer types." (PMID 40233410, 2025).
cancer (continued). "These genes are involved in the regulation of cell cycle (CCND1, CDCA5, FOSL1, KDM2A, NUMA1, RHOD), apoptosis (FADD, ORAOV1), or the DNA damage response (DDB1, KAT/TIP60, MUS81, PACS1, RPS3), and several have been implicated in the HPV lifecycle and/or HPV-associated cancers." (PMID 40892869, 2025). "In cancer cells, mutations in APC or β‐catenin, or excessive Wnt ligand activation, result in β‐catenin accumulation and nuclear translocation, where it acts as a transcriptional co‐activator of oncogenic genes, such as c‐Myc, cyclin D1, and matrix metalloproteinases (MMPs)." (PMID 40387523, 2025). "By interaction with Gli2, CCND1 could promote cancer cell proliferation." (PMID 40478912, 2025). "Increased NF-κB transcriptional activity has a stimulating effect on the process of cancer cell proliferation by facilitating the transition of cells from the G1 phase to the S phase of the cell cycle as a result of transcription stimulation, among others, cyclin D1." (PMID 39124936, 2024). "As a result, targeted destruction of CCND1 may be an interesting target for cancer treatment." (PMID 38326490, 2024). "Silencing FBXO9 in A549 cancer cells by siRNA transfection substantially increased the expression of active β-catenin (the primary effector of the canonical Wnt signaling pathway), C-Myc and cyclin D1 (both important downstream targets of this pathway) upon FBXO9 depletion." (PMID 38486234, 2024). "Overexpression of STAT3 has been linked to cancer, and CPT treatment slows the growth of cancer by blocking STAT3 by selectively decreasing STAT3 Tyr705 phosphorylation and its downstream target proteins, which include Bcl-xL, survivin, and cyclin D1 in prostate cancer." (PMID 38397437, 2024). "In stages, CCND1 revealed statistical significance between normal and all stages in COAD, ESCA, KIRC, READ, STAD, and THCA, and it could be used as a diagnostic biomarker in these types of cancer." (PMID 39188436, 2024). "Additionally, cancer cells may upregulate cyclin D1 as a compensatory mechanism to counteract drug effects and maintain proliferation, leading to drug resistance." (PMID 39682189, 2024). "Additionally, Cyclin D1/CDK4-Rb pathway regulates the metastatic capacity of cancer cells." (PMID 39161904, 2024). "The transcriptional activation of oncogenes such as C-myc and cyclin D1 by F. nucleatum is mediated via the upregulation of β-catenin signaling, suggesting a direct mechanistic link between microbial infection with subsequent epigenetic modifications leading to cancer induction." (PMID 39409925, 2024). "Inhibition of SAAL1 expression could regulate cancer growth via cyclin D1 and Bcl-2." (PMID 36973678, 2023). "For instance, HSPA8 supports the assembly and activity of the cyclin D1 holoenzyme by binding and folding freshly generated cyclin D1, and cyclin D1 is amplified and overexpressed in a variety of malignancies, where it speeds up the proliferation of cancer cells." (PMID 37771276, 2023). "Thus, it is highlighting significance of aberrant isoforms of CCND1 as targets for cancer therapy." (PMID 37024471, 2023). "In addition, genistein is known to lower cyclin D1 expression levels in different types of cancer." (PMID 36905879, 2023). "The inhibition of mTOR may have antiproliferative effects with several mechanisms including a selective decrease in the translation of mRNAs (such as c‐myc, VEGF) essential to tumorigenesis and a decreased phosphorylation of cyclin D1 leading to cycle progression arrest in cancer cells." (PMID 36205189, 2023). "However, CCND1 is often abnormal expressed in many cancers, including HCC." (PMID 36937431, 2023).
cancer (continued). "Therefore, targeting the CCND1 gene may offer a promising strategy to overcome drug resistance in cancer treatment." (PMID 37744271, 2023). "Interestingly, exogenous MG53 expression could dose-dependently repress the proliferation of cancer cells with relatively abundant cyclin D1 protein, but had very limited effects on cells with little cyclin D1." (PMID 37414783, 2023). "NF-κB falls into the category of a nuclear factor that binds to the gene regulatory region encoded by the immunoglobulin k light chain of activated B cells, and the abnormal activation of NF-κB could enhance cancer cell proliferation by binding to the cyclin D1 promoter." (PMID 36199554, 2022). "Additionally, we evaluated the expression of some cancer‐related proteins in ex vivo tumors from both groups, including proliferation (Ki‐67 and Cyclin D1), anti‐apoptotic (BCL2), and stemness (NESTIN and SOX2) markers, collected at distinct time points according to animal survival times." (PMID 34919784, 2022). "We analyzed circulating cell-free DNA (cfDNA) extracted from plasma using high-depth massively parallel sequencing targeting 468 cancer-associated genes, and we identified a clonal hotspot missense mutation in the PIK3CA gene (3:178952085, A > G, H1047R) and amplification of the CCND1 gene." (PMID 36551247, 2022). "Importantly, a cancer-specific H3K4me3-BD is observed covering most of the CCND1 gene body." (PMID 34933939, 2022). "Depletion of FOXO1 could promote cancer cell proliferation by enhancing cyclin D1 expression." (PMID 36210843, 2022). "Furthermore, CCND1 is a target of immunotherapy for numerous cancers." (PMID 35665333, 2022). "Therefore, the overexpression of cyclin D1 or the failure of cyclin D1 degradation both accelerate G1-S transition, helping cancer cells to gain a survival advantage and an uncontrolled proliferation, which further promotes the invasiveness and malignance of cancer." (PMID 36059670, 2022). "It shows that cyclin D1 may be a potential therapeutic target in cancer therapy." (PMID 34335935, 2021). "Furthermore, we uncovered a potential correlation between p-ERK1/2, β-catenin, S6K, and cyclin D1, which might be responsible for the anti-cancer effect of MH or combined treatment." (PMID 34049576, 2021). "Interestingly, some reports also have suggested that Akt1 might target some proteins, such as β-catenin and cyclin D1, to alter the progression of cancer through regulating cell proliferation and migration." (PMID 33911067, 2021). "It was revealed that apelin could promote cancer cell proliferation by increasing expression of factors involved in cell proliferation including cyclin D1, Ki-67, proliferating cell nuclear antigen (PCNA), and activating pathways like JAG1/Notch3, ERK1/2, and PI3K/Akt." (PMID 33912466, 2021). "Likewise, CCND1 (cyclin D1) is amplified or overexpressed in cancer and may cooperate with MYC to promote transformation." (PMID 33996588, 2021). "Beyond the known targets of YAP (i.e., MYC and CCND1), we uncovered TRAM2 (translocation chain-associated membrane 2) and described its contribution to cellular proliferation, epithelial to mesenchymal transition (EMT), and cellular migration and invasion, as well as cancer prognosis." (PMID 33514403, 2021). "This may be explained by different effects of CCND1 down-regulation in cancer cells." (PMID 33923996, 2021). "Besides, ISL1 was also verified to be a novel regulator of the cyclin D1 and c-Myc genes in cancer, and it could predict prognostics for cancers like gastric cancer, bladder cancer, and may also act as a biomarker in NB." (PMID 34131100, 2021). "Thus, cyclin D1 has been an area of focus in cancer research." (PMID 34539418, 2021). "Salinomycin sensitizes paclitaxcel-, docetaxcel-, vinblastin-, or colchicine-treated cancer cell lines; on one side salinomycin increases pH2AX level and reduces p21 level; this leads to mitotic catastrophe; on the other side, salinomycin reduces cyclin D1 level to prevent G2 arrest." (PMID 34381705, 2021).